HTR1F (5-hydroxytryptamine receptor 1F)
Description:
G protein-coupled receptor for 5-hydroxytryptamine (serotonin). Also functions as a receptor for various alkaloids and psychoactive substances. Receptor for lasmiditan, a drug for the treatment of acute migraine. Ligand binding causes a conformation change that triggers signaling via guanine nucleotide-binding proteins (G proteins) and modulates the activity of downstream effectors, such as adenylate cyclase. HTR1F is coupled to G(i)/G(o) G alpha proteins and mediates inhibitory neurotransmission by inhibiting adenylate cyclase activity.
Synonyms: 5-HT-1F; 5-HT1F; HTR1EL; 5HT6; MR77
Tractability: Small molecule: an approved drug acts on it; a structure with a bound ligand is known; a high-quality ligand is known; it belongs to a druggable protein family. Antibody: UniProt places it where antibodies can reach, with high confidence; its Gene Ontology location is reachable by antibodies, with high confidence; UniProt predicts a signal peptide or a membrane-spanning region. PROTAC: a small molecule that binds it is known.
Target class: Monoamine receptor; Family A G protein-coupled receptor; Small molecule receptor (family A GPCR); Serotonin receptor; Membrane receptor
Chemical probes: CHEMBL3617550
Gene: Protein-coding gene on chromosome 3 (87,792,704 to 87,993,839, forward strand). Ensembl gene ENSG00000179097.
Subcellular location: Cell membrane
Pathways (Reactome):
Signal Transduction: G alpha (i) signalling events; Serotonin receptors
Gene Ontology:
Molecular function: G protein-coupled serotonin receptor activity; Gi/o-coupled serotonin receptor activity; protein binding; serotonin binding; neurotransmitter receptor activity; G protein-coupled receptor activity
Biological process: adenylate cyclase-inhibiting G protein-coupled receptor signaling pathway; adenylate cyclase-inhibiting serotonin receptor signaling pathway; chemical synaptic transmission; G protein-coupled receptor signaling pathway, coupled to cyclic nucleotide second messenger; G protein-coupled receptor signaling pathway
Cellular component: plasma membrane; dendrite; membrane; synapse
Genetic constraint (gnomAD): Loss-of-function variants: 17 observed, 25.22 expected, observed/expected ratio (o/e) 0.67, 90% interval 0.46 to 1.01. The upper end of that interval is the gene's LOEUF score, 1.01, which puts it in group 4 of 6, group 1 being the genes least tolerant of losing a copy. Missense variants: 391 observed, 450.97 expected, observed/expected ratio (o/e) 0.87, 90% interval 0.8 to 0.94. Synonymous variants: 186 observed, 166.2 expected, observed/expected ratio (o/e) 1.12, 90% interval 0.99 to 1.26.
Homologues: Orthologues: chimpanzee HTR1F (100% identical), rabbit HTR1F (96% identical), dog HTR1F (94% identical), mouse Htr1f (94% identical), pig HTR1F (94% identical), rat Htr1f (92% identical), tropical clawed frog htr1f (78% identical), Drosophila melanogaster 5-HT1A (38% identical), Drosophila melanogaster 5-HT1B (37% identical). Paralogues in human: HTR1E (56% identical), HTR1B (47% identical), HTR7 (34% identical), HTR5A (33% identical), HTR2A (30% identical), HTR2C (28% identical), HTR2B (27% identical), HTR6 (26% identical).
Diseases named in the same sentence as HTR1F in open-access papers:
HTR1F is named in the same sentence as 19 diseases in open-access papers, as found by Europe PMC text mining. Sharing a sentence is not in itself a finding about the gene and the disease. The quoted sentences say what the papers report.
migraine (7 papers, 2020 to 2024). "Two of the new risk loci contain genes (CALCA/CALCB and HTR1F) whose protein products are closely related to targets of two migraine-specific drug therapies." (PMID 35115687, 2022). "Newly detected loci encoded migraine drug targets, such as CGRP (CALCA/CALCB) and serotonin 1F receptor (HTR1F)." (PMID 37755358, 2023). "The new risk loci include genes encoding recent migraine-specific drug targets, namely calcitonin gene-related peptide (CALCA/CALCB) and serotonin 1F receptor (HTR1F)." (PMID 35115687, 2022). "Studies in humans also strongly support the hypothesis that HTR1F plays a major role in migraines and is a potential anti-migraine drug target." (PMID 34207786, 2021).
acute myeloid leukemia (2 papers, 2024 to 2025). Acute myeloid leukemia (AML) is a group of neoplasms arising from precursor cells committed to the myeloid cell-line differentiation. "Another bioinformatics analysis related to leukemia indicated that HTR1F could have a crucial role in RUNX1 mutation acute myeloid leukemia (AML)." (PMID 41007799, 2025). "HTR1F was highly expressed in KIRC, acute myeloid leukemia (LAML), and thymoma (THYM) and lowly expressed in BRCA CESC, LUAD, LUSC, UCEC, and UCS." (PMID 39766808, 2024).
breast carcinoma (1 paper, 2009). "Expression levels for HTR1F, 2B, 2C, 5A and 7 showed overall increases in breast cancers." (PMID 19903352, 2009).
gastric cancer (1 paper, 2025). A primary or metastatic malignant neoplasm involving the stomach. "Representative immunohistochemistry images of HTR1F expression in normal and cancerous human tissues, including renal cancer, glioma, and stomach cancer, are shown from the Human Protein Atlas database." (PMID 41007799, 2025).
Headache (1 paper, 2022). Cephalgia, or pain sensed in various parts of the head, not confined to the area of distribution of any nerve. "The expression of 5‐HT receptor genes, Htr1a, Htr1f, and Htr2c, was found to be activated in this study and contributed to headaches and behavioral inhibition in mice." (PMID 36514756, 2022).
lung squamous cell carcinoma (1 paper, 2025). "Validation experiments confirmed that HTR1F has oncogene function and promotes the proliferation of lung squamous cell carcinoma (LUSC) through the MAPK pathway." (PMID 41007799, 2025). "Based on our previous findings, HTR1F was identified as an independent prognostic indicator for patients with lung squamous cell carcinoma (LUSC)." (PMID 41007799, 2025). "To validate the functional role of HTR1F in lung squamous cell carcinoma (LUSC), we performed HTR1F overexpression experiments in two LUSC cell lines, NCI-H226 and NCI-H520." (PMID 41007799, 2025). "Finally, the biological function of HTR1F was validated in vitro using lung squamous cell carcinoma (LUSC) cell lines, where HTR1F overexpression was found to promote cell proliferation through activation of the MAPK signaling pathway." (PMID 41007799, 2025).
cancer (4 papers, 2015 to 2025). A tumor composed of atypical neoplastic, often pleomorphic cells that invade other tissues. "Although dysregulated HTR1F expression has been implicated in certain malignancies, its biological functions and clinical significance across cancer types remain largely unexplored." (PMID 41007799, 2025). "Furthermore, the prognosis analysis of HTR1F gene expression in pan-cancer indicated a poor prognosis associated with the high expression of HTR1F in four tumor types—LUSC, KIRP, STAD, and UVM." (PMID 41007799, 2025). "Taken together, these limitations highlight the need for further experimental and clinical investigations to clarify the context-dependent functional roles of HTR1F across different cancer types." (PMID 41007799, 2025). "Together, our findings provide novel insights into the role of HTR1F in cancer progression and its potential as a therapeutic target." (PMID 41007799, 2025). "Consistent findings were obtained using the CIBERSORT algorithm, which demonstrated that HTR1F expression is significantly related to 22 immune cell subsets across 42 commonly studied cancers." (PMID 41007799, 2025). "While this study represents the first comprehensive investigation into the role of HTR1F in cancer, several limitations should be acknowledged." (PMID 41007799, 2025). "A positive expression of HTR1F in the mucous membrane tissues of colon cancer patients is reported to be significantly higher than that in the adjacent cancers." (PMID 41007799, 2025). "Gene Set Enrichment Analysis (GSEA)-based GO and KEGG enrichment analyses, using TCGA pan-cancer datasets, indicated that HTR1F is primarily involved in nuclear division–related biological processes and signaling pathways such as the cell cycle, cellular senescence, and oocyte meiosis." (PMID 41007799, 2025). "Furthermore, aberrant HTR1F expression across pan-cancer was found to correlate significantly with the extent of immune cell infiltration, the expression levels of immune checkpoint molecules, and key genomic features such as tumor mutational burden (TMB) and microsatellite instability (MSI)." (PMID 41007799, 2025). "However, current evidence regarding the oncological roles of HTR1F is limited to a few cancer types, and its broader relevance across diverse tumor types remains unclear." (PMID 41007799, 2025). "In the case of G3 cancer, a decrease in HTR2B expression and the overexpression of HTR1A and HTR1F were also noted." (PMID 34768392, 2021).
tumor (1 paper, 2025). "HTR1F expression correlated with immune-related genes, immune checkpoints, tumor-infiltrating immune cells, tumor mutation burden (TMB), microsatellite instability (MSI), and drug responses." (PMID 41007799, 2025). "In summary, our study revealed that HTR1F is markedly overexpressed in multiple tumor types, with its dysregulated expression closely linked to patient prognosis." (PMID 41007799, 2025). "This widespread association suggests that HTR1F may play an important role in modulating the immune landscape of tumors, potentially influencing both tumor progression and therapeutic response." (PMID 41007799, 2025). "This study focused on analyzing the mutation patterns of HTR1F across various tumor types." (PMID 41007799, 2025). "The mRNA expression profile of HTR1F was assessed across multiple tumor types using RNA-seq data from 34 TCGA, TARGET, and GTEx cohorts (PANCAN, N = 19,131; G = 60,499) obtained from the UCSC database." (PMID 41007799, 2025). "According to these findings, HTR1F could have an essential role in the regulation of the tumor microenvironment." (PMID 41007799, 2025).
HTR1F also shares sentences with these, for which no sentence is quoted: schizophrenia (2 papers); acute kidney injury (1); breast adenocarcinoma (1); colon cancer (1); glioma (1); infection (1); osteosarcoma (1); ovarian carcinoma (1); renal carcinoma (1); stomach cancer (1); thymoma (1).